ARHGAP29 (Rho GTPase activating protein 29)
Diseases named in the same sentence as ARHGAP29 in open-access papers (continued):
Sharing a sentence is not in itself a finding about the gene and the disease.
migraine without aura (1 paper, 2022). A migraine disorder characterized by episodes that occur in the absence of preceding focal neurological symptoms. "The study identified genes correlated with SCD that were associated with episodic migraine (rs144191744), chronic migraine (rs4488224 in LOC107984361 and rs17111203 in ARHGAP29), and migraine without aura (rs112400385 in ST18 and rs144191744)." (PMID 35783123, 2022). "Although this study did not screen for other known Rho GTPases genes related to migraine, SCD, or AD, we believe that ARHGAP29 is a potential gene that warrants further in-depth research." (PMID 35783123, 2022).
renal carcinoma (1 paper, 2020). A carcinoma arising from the epithelium of the renal parenchyma or the renal pelvis. "In renal cancer cells, the ability to migrate and invade can be significantly increased by overexpression of ARHGAP29." (PMID 33291460, 2020).
tumor (9 papers, 2017 to 2025). "The results indicated that ARHGAP29 expression was significantly higher in tumor samples, while GNLY and NRIP1expression was significantly lower in UCEC samples." (PMID 36568182, 2022). "Interestingly, our data showed that ARHGAP29 expression is promoting tumor cell plasticity through a mesenchymal-like, invasive phenotype." (PMID 40906537, 2025). "Despite this, it remains unclear as to whether ARHGAP29 is involved in the local invasion of tumor cells." (PMID 33291460, 2020). "Regarding the contradicting data on the role of AKT1 in the invasion of tumor cells and the poor knowledge of signaling around ARHGAP29 and AKT1, possible crosstalk between ARHGAP29 and AKT1 signaling should be investigated in detail." (PMID 33291460, 2020).
cancer (6 papers, 2020 to 2025). A tumor composed of atypical neoplastic, often pleomorphic cells that invade other tissues. "We became interested in ARHGAP29, a putative RhoA GAP that is upregulated in many migratory cancer types and has variants that cause cleft palate." (PMID 41200767, 2025). "The expression of another YAP target, ARHGAP29 (Rho GTPase-activating protein 29), has been shown to correlate with the metastatic potential of several cancers." (PMID 37835395, 2023). "One of these proteins, the RhoGAP ARHGAP29, has been shown to regulate mechanotransduction in a YAP-dependent manner and to control cancer cell migration and invasion by suppressing actin polymerisation through a Rho/LIMK/cofilin pathway." (PMID 39315773, 2024). "Furthermore, RhoA inactivating regulator, i.e., Rho GTPase activating protein 29 (ARHGAP29), has been shown to regulate cancer cell metastasis via RhoA/LIMK/CFL-1 signal." (PMID 37193711, 2023).
ARHGAP29 also shares sentences with these, for which no sentence is quoted: infection (3 papers); bladder cancer (1); cervical cancer (1); chronic kidney disease (1); cleft lip and palate (1); cognitive defects (1); Ectrodactyly (1); esophageal carcinomas (1); focal segmental glomerulosclerosis (1); glioblastoma (1); Hepatitis (1); hypertensive nephropathy (1); minimal change disease (1); neurological diseases (1); osteoporosis (1); pancreatic ductal adenocarcinoma (1); schizophrenia (1).